INS (insulin)
Diseases named in the same sentence as INS in open-access papers (continued):
Sharing a sentence is not in itself a finding about the gene and the disease.
tumor (continued). "Although the anti-tumour mechanism of action of metformin is not yet clear, its anti-tumour effects in breast cancer are suggested to be via an indirect pathway by decreasing both insulin plasma levels and inhibiting downstream PI3K and mitogen-activated protein kinase (MAPK) signalling." (PMID 27903276, 2016). "In this scenario the insulin analogues could act either as a tumor initiator by transforming benign or (pre)neoplastic cells, which often express increased levels of IRA and IGF1R, or as a tumor promoter by stimulating the increased growth potential of these cells." (PMID 26187749, 2015). "In addition to inhibiting activation of the insulin-dependent PI3K/Akt/mTOR pathway, several studies have shown that metformin inhibits mTOR activation through activation of AMPK, which is also a critical mechanism of metformin in exerting its anti-tumor effects." (PMID 25879666, 2015). "Thus, metformin may have a direct effect on tumor cells independent of its effects on circulating insulin and IGF-1." (PMID 24133632, 2013). "Consequently, metformin may diminish the negative effects of insulin on tumor development and growth." (PMID 21470407, 2011). "The positive correlations observed between serum Ang-2 and serum C-peptide (a stable marker of circulating insulin levels), and between VEGF-A and IGF-1 in males, may implicate insulin and IGF-1 in promoting a systemic pro-angiogenic environment, and potentially increasing tumour angiogenesis." (PMID 21081932, 2011). "However, CDSF includes LIF and insulin, and failed to support the tumor-like growth of mESCs." (PMID 21731714, 2011). "Risk score was significantly positively correlated with most of the tumor-related signaling pathways, such as MTOR, Insulin, ERBB and Wnt signal pathways, while significantly negatively related to PPAR and Notch signaling pathways." (PMID 38685045, 2024). "Analysis of insulin and related glucoregulatory hormone secretion following high-molecular-weight insulin-like growth factor II (HMW-IGF-II)-releasing tumor excision has never been reported." (PMID 37908273, 2022). "In contrast, amylase, insulin, glucagon, and CK19 expression was largely absent in neoplasm in the pancreas of Pdx-1CreLKB1L/L mice that received the vehicle (DMSO)." (PMID 33924999, 2021). "By comparison, plasma insulin levels increased at similar rates in both RT2 and RT2; R6KO mice (males and females) over time regardless of differences in tumor burden." (PMID 34199469, 2021). "Similar to insulin NPH, chronic exposure to insulin glargine did not significantly affect tumor latency time compared to the vehicle treatment, although tumors developed slightly earlier in the glargine treated animals." (PMID 25848982, 2015). "While a low carbohydrate diet does not consistently lower serum insulin and insulin-like growth factor (IGF) levels in tumor animal models, in our mice we did see a significant reduction in insulin." (PMID 26192445, 2015). "In contrast, metformin prevented tumor formation in a toxin-mediated mouse model of lung cancer while reducing circulating IGF-1 and insulin levels, but without demonstrated ability to activate AMPK in lung tissue." (PMID 25361177, 2014). "There were no major differences in non-fasting blood insulin or blood glucose levels at 10 weeks on LFD or HFD, or in HFD-E and LFD tumor-bearing mice." (PMID 24156623, 2013). "However, the results were derived from studies conducted over a relatively short period of time (5 years), potentially suggesting that insulin (glargine) may accelerate the rate of development of existing tumours rather than stimulating malignant transformation and the formation of new ones." (PMID 19804622, 2009). "Tumours and abdominal adipose tissue (AAT) had 4-6 and 1.4-1.7 times as much insulin as non-cancerous control organs." (PMID 7981074, 1994).
tumor (continued). "This is in line with previous reports that have shown systemic dysregulation of the insulin/IGF pathway in PDAC, which may not directly mirror the gene-expression profiles within the tumor itself." (PMID 40699634, 2025). "Therefore, the protective role of metformin would not be attributable to its indirect action as an insulin-sensitizer, but to the direct activation of AMPK and the consequent influence on tumor cell metabolism." (PMID 33713207, 2021). "Tumor weight correlated positively with glucose (rs = 0.50, P < 0.001), HOMA-IR (rs = 0.45, P = 0.001), leptin (rs = 0.34, P = 0.017), and visfatin (rs = 0.49, P < 0.001) but is not correlated with insulin (rs = 0.26, P = 0.064)." (PMID 33381605, 2020). "This anti-proliferative effect may constitute a direct toxic and apoptosis-inducing effect on the tumor cells, but also can potentially be mediated through TCM herbal effects on non-tumor factors such as estrogens or insulin." (PMID 28769793, 2017). "Although the effects of insulin on tumor 18 F-FDG uptake have been studied by others before, the prior studies all involved insulin injections into the animal or patient that yielded a non-steady state circulating insulin level and also a variable blood glucose level at the same time." (PMID 23841937, 2013). "The EANM Procedure Guidelines for Tumour Imaging: Version 2.0 recommend that FDG injection should be administered no sooner than 4 h after the subcutaneous administration of rapid-acting insulin, and no sooner than 6 h after the administration of short-acting insulin." (PMID 39412643, 2025). "Tumours not expressing an abundance of SSTR-2 over SSTR-5 subtypes may have reduced response to these agents and may, in fact, experience preferential suppression of glucagon over insulin, leading to hypoglycaemia." (PMID 40697399, 2025). "Moreover, because tumor removal surgery might induce chronical infection resulting in post-operative complications and tumor recurrence, a phase 4 clinical trial not yet recruiting (NCT02746432) proposes the use of insulin therapy during colon cancer surgery." (PMID 30781344, 2019). "Therefore, it is worth further investigating whether or not insulin could play a role in regulating SESN2 content in vivo and its pathological significance in a variety of metabolic and tumor diseases." (PMID 25792980, 2015). "Animals bearing the MAC16 tumour had a reduced nitrogen balance compared with non-tumour-bearing controls, mainly due to excess urea excretion, and this was reversed towards control values in animals fed an 80% MCT diet, but not in animals administered insulin." (PMID 2736199, 1989).
cardiovascular disease (1,253 papers, 2005 to 2026). "Adiponectin is an adipocytokine that regulates metabolism, insulin sensitivity, and inflammation, and increased adiponectin levels have been associated with mortality in subjects with cardiovascular diseases." (PMID 41602445, 2026). "Our previous work has shown that glucose autocorrelation is influenced by insulin clearance, a process known to be associated with cardiovascular disease risk." (PMID 41537426, 2026). "Excessive lipid accumulation in the circulation disrupts glucose metabolism, which contributes to insulin resistance and pancreatic β-cell dysfunction, ultimately elevating the risk of cardiovascular disease." (PMID 41356015, 2025). "The insulin-deficient subtypes accounted for the greatest estimated reductions in life expectancy for both all-cause and cardiovascular disease mortality (Table-2)." (PMID 40678231, 2025). "Sotagliflozin, when used in combination with insulin therapy, resulted in significant reductions in cardiovascular disease (CVD) risk (−6.38%; 95% CI: −7.63 to −5.1; P < 0.05) and end-stage kidney disease (ESKD) risk (−5.0%; 95% CI: −7.62 to −2.3; P < 0.05)." (PMID 40529829, 2025). "Phospholipid insufficiency has also been linked with impaired insulin signaling and a higher risk of cardiovascular disease, possibly due to compromised membrane fluidity and diminished capacity for NO production." (PMID 40548377, 2025). "For T2DM patients with milder cardiovascular diseases such as AF, insulin use increased the risk of HF events, cardiovascular and all‐cause mortality." (PMID 41320960, 2025). "Leading to decreased insulin sensitivity, which is a known risk factor for various cardiovascular diseases." (PMID 40066350, 2025). "Preserved endothelial insulin signaling and balanced insulin–aldosterone levels enhance nitric oxide availability, reducing vascular stiffness and cardiovascular disease risk." (PMID 40507062, 2025). "This concept aligns with the broader framework in which chronic insulin elevation precedes and drives pathophysiological cascades implicated in cardiovascular disease, oestrogen-dependent cancers, PCOS, and neurodegeneration." (PMID 41586225, 2025). "Our findings are consistent with a recent meta-analysis showing that metformin and GLP-1 receptor agonists (GLP-1 RAs) can improve insulin sensitivity, reduce testosterone levels, and mitigate the risk of cardiovascular disease in women with PCOS." (PMID 40564951, 2025). "Studies have shown that regular consumption of EVOO improves gut microbial diversity, reduces the risk of cardiovascular diseases, and enhances metabolic parameters such as insulin sensitivity." (PMID 40289944, 2025). "Engaging in sufficient and regular aerobic or resistance exercise can also reduce the risk of cardiovascular disease and high BMI, as well as improve insulin resistance." (PMID 39896196, 2024). "By decreasing oxidative stress and inflammatory markers, insulin helps mitigate the risk of cardiovascular diseases associated with chronic inflammation." (PMID 39125938, 2024). "Patients with cardiovascular disease or impaired renal function require careful monitoring, and there is an increased risk of ketoacidosis, especially in those with low insulin levels or on low-carbohydrate diets." (PMID 39728750, 2024). "The Mediterranean diet, which includes a variety of fruits, vegetables, whole grains, and healthy fats, has been shown to improve insulin sensitivity and reduce the risk of cardiovascular disease." (PMID 39337658, 2024). "This is important since preserving lean body mass is not only essential for weight loss sustainability but is also known to be a protective factor for cardiovascular diseases and is associated with greater insulin sensitivity." (PMID 38794747, 2024). "Various studies have suggested that high-saturated-fat diets (HFDs) are associated with an increased risk of cardiovascular diseases and diabetes involving insulin signaling pathways and pro-inflammatory cytokines." (PMID 39796562, 2024).
cardiovascular disease (continued). "Specifically, physical activity reduces the risk of cardiovascular disease through multiple mechanisms, including lowering blood pressure, improving cholesterol levels, increasing insulin sensitivity, and reducing inflammation." (PMID 38137886, 2023). "The Centers for Disease Control and Prevention (CDC) states that high-fat diets impair insulin sensitivity and lipid metabolism, and thus increase the risk of cardiovascular disease." (PMID 37958546, 2023). "Gulbahar and colleagues demonstrated that measuring serum zinc, total cholesterol, fasting insulin, and fasting blood glucose levels is a practical method for monitoring postmenopausal women with high cardiovascular disease (CVD) risk profiles." (PMID 38248733, 2023). "Fiber, one of the crunchy foods, is associated with improved insulin sensitivity and cardiovascular disease, colon health, bowel motility, and multiple medical conditions." (PMID 37299565, 2023). "Lignans have been associated with a reduced risk of breast and prostate cancer and cardiovascular disease, and improved insulin sensitivity." (PMID 37896042, 2023). "Studies have demonstrated that fasting during Ramadan has been shown to increase HDL cholesterol, leptin, adiponectin, and insulin sensitivity, as well as lower several hemostatic risk factors for cardiovascular diseases." (PMID 38169925, 2023). "Participants were sorted according to presence of ≥1 MetS criteria and meeting criteria for ISI-cal insulin sensitivity index for future risk of cardiovascular disease." (PMID 36352897, 2022). "Rumenic acid has been related to positive effects on serum lipid profile, blood glucose, insulin sensitivity, blood pressure, and cardiovascular disease risk factor in humans." (PMID 35782564, 2022). "Previous studies have demonstrated the positive associations between circulating concentration of TMAO and cardiovascular disease risk and have suggested the adverse effects on specific cardiometabolic biomarkers, such as homocysteine, insulin and glucose." (PMID 35982495, 2022). "The exercise-induced improvement in insulin sensitivity and lipid profile justifies the reduction in the risk of death from cardiovascular disease." (PMID 35324639, 2022). "Exercise interventions in overweight/obese individuals can reduce blood sugar levels and improve insulin sensitivity, thereby reducing the risk of cardiovascular disease." (PMID 35655279, 2022). "DHEA has been shown to increase insulin sensitivity as well as predict all-cause and cardiovascular disease death." (PMID 36065220, 2022). "Future work should consider assessing the association of aortic waveform responses to insulin relative to aerobic fitness and metabolic function in later chronotype in the hopes of addressing cardiovascular disease risk prevalent within this classification." (PMID 36301720, 2022). "Insulin, which remains the exclusive glucose-lowering agent in persons with T1D, does not permit modification of the metabolic risk profile associated with cardiovascular disease." (PMID 35745754, 2022). "From an endocrinological point of view, insulin seems to be the main driver of cardiovascular disease risk in patients with PCOS." (PMID 35877459, 2022). "It is widely recognized that MD has beneficial effects on cardiometabolic health, including blood pressure, insulin sensitivity, and lipid profile, thus decreasing the risk of cardiovascular disease." (PMID 35326149, 2022). "Fish is high in omega-3 fatty acids (n-3 FAs), which exert protective properties against AD by their ability to reduce oxidative stress, to lower insulin and cholesterol levels and to decrease the risk for cardiovascular disease." (PMID 36188390, 2022). "It involves either a deficiency in insulin secretion, resistance to insulin action, or both, and can also be associated with lipid disorder, cardiovascular disease, retinopathy, and other pathologies." (PMID 33613154, 2021).
cardiovascular disease (continued). "Low level of education and high BMI poorly affected glycaemic control whiles being on insulin therapy and having a cardiovascular disease were also found to be positively associated with one’s glycaemic control." (PMID 34936668, 2021). "These included ratios associated with lipase activity, elongases, docosahexaenoic acid (DHA) levels, dairy fat intake, insulin production, glucose control, de novo lipogenesis, and cardiovascular disease risk." (PMID 34503513, 2021). "South Asian adolescents are more insulin resistant, have more body fat, and have a higher risk of cardiovascular disease with higher blood pressure and fasting triglycerides compared to white British adolescents." (PMID 34836031, 2021). "The metabolic changes induced by the life-long derangement of insulin, glucose, and lipid levels can lead to an increased risk of cardiovascular disease in patients with T2D." (PMID 34093440, 2021). "Overall, high BMI and use of insulin therapy were associated with poor glycaemic control (high HbA1c) whereas low levels of coffee intake and having a cardiovascular disease were positively associated with glycaemic control." (PMID 34936668, 2021). "In contrast, some large observational studies have come to another conclusion, suggesting an association between insulin therapy in people with T2D and cardiovascular disease or premature death." (PMID 34615525, 2021). "Decreased levels of this fat-derived hormone are supposed to be associated with insulin sensitivity, and with glucose and lipid metabolism and cardiovascular disorders." (PMID 32326591, 2020). "Since these are chronic treatments, it would be interesting to evaluate the factors underlaying the single dispensing of insulin and treatments for cardiovascular disease." (PMID 32408626, 2020). "Short-term CR can improve insulin sensitivity and reduce the risk of cardiovascular diseases, indicating its potential benefit for human health." (PMID 32082101, 2020). "This study aimed to investigate the association between adipocytokines and insulin patterns with the risk of cardiovascular diseases." (PMID 32290863, 2020). "The present study was conducted to investigate the association of dietary insulin index(II), insulin load(IL), glycemic index(GI), and glycemic load(GL) with the risk of cardiovascular disease(CVD)." (PMID 33008356, 2020). "Mechanisms by which cardiovascular diseases progress include the loss of metabolic balance between glycolipid synthesis and energy consumption in insulin-sensitive organs." (PMID 32478098, 2020). "This advantage would add to the other positive effects of consuming this type of protein in menopause, such as decreasing bone loss and risk of hip fracture, improving insulin sensibility and decreasing cardiovascular disease risk." (PMID 32824413, 2020). "In epidemiological studies, high-dose insulin therapy is associated with an increased risk of cardiovascular disease." (PMID 32819363, 2020). "Monocyte numbers are typically increased with chronic infection, but elevated concentrations are also associated with worsening of insulin sensitivity and most recently noted to be a risk factor for cardiovascular disease." (PMID 32545396, 2020). "Proof for a causal link between elevated insulin levels and cardiovascular disease risk comes from Mendelian randomization studies comparing individuals with genetically controlled low or high insulin production." (PMID 32819363, 2020). "The level of glutamine and the ratio of Gln to Glu were negatively correlated with the risk factors of cardiovascular disease (including body mass index, waist circumference, fasting blood glucose, insulin, triglyceride, etc.)." (PMID 33505234, 2020). "It helps to improve glucose and insulin metabolism and effectively decreases the risk factors for cardiovascular diseases." (PMID 31842522, 2019).